CD3E (CD3 epsilon subunit of T-cell receptor complex)
Diseases named in the same sentence as CD3E in open-access papers (continued):
Sharing a sentence is not in itself a finding about the gene and the disease.
tumor (continued). "Using an anti-CD3ε mAb, anti-FOLR1 mAb, and anti-MSLN mAb, we examined the distribution of T cells and expression of FOLR1 and MSLN in tumor samples from mice by IHC analysis." (PMID 34803504, 2021). "The expression of LCK and CD3E was found to be much lower in tumor samples than in normal samples, with a median expression value (transcript per million) of 6.685 vs 3.116 for LCK and 17.484 vs 5.58 for CD3E." (PMID 35004669, 2021). "We adjusted these results based on tumor purity, revealing strong and significant correlations between CD96 and CD8+ T cell markers (CD8A), general T cell markers (CD3D, CD3E, CD2), DC markers (HLA-DPB1, HLA-DRA, HLA-DPA1) in LGG." (PMID 33680972, 2021). "Upon challenge, however, low levels of IL-15 were more protective and resulted in a greater production of anti-tumor cytokines such as IFN-γ and MIP-1β and a greater amount of CD11b+ and CD3e+ cells infiltrating tumors." (PMID 33096755, 2020). "Despite these distinct tumor types, evaluation of RNA counts across samples for CD45 correlated with CD3E and with CD68 (p < 0.0001)." (PMID 33228231, 2020). "In mice, the CD3 signaling complex was recently successfully manipulated by a mono Fab anti-CD3ε therapy is able to boost the activation of antigen-specific CD8+ T cells and results in decreased tumor burden." (PMID 30735510, 2019). "A more recent promising therapeutic approach involves redirecting T cells to attack tumor cells by using BsAbs that bind to a tumor expressing target and common surface component of the T cell receptor (TCR) (e.g., CD3e)." (PMID 30886871, 2019). "The combinatorial use of anti-CD3ε Fab and anti-PD1 has been shown to further increase the control of tumor metastases over the use of anti-CD3ε alone." (PMID 30735510, 2019). "This surprising increase of T cell activity from spleens of older hosts due to CD2, CD3ε, CCL19, and CCL5 directly has impacted the decrease in tumor growth we observed in our earlier publication." (PMID 26497558, 2015). "All key molecules in the spleen of tumor bearing old hosts (CD2, CD3ε, CCL19, and CCL5) (also been reported to exist in the spleen) leads to immune cell survival and function through increased T-cell survival and activity." (PMID 26497558, 2015). "It was revealed that the following immune related factors were key factors being commonly up-regulated for old tumor bearing hosts compared to all younger age groups: CD2, CD3ε (or CD3E), CCL19, and CCL5." (PMID 26497558, 2015). "Mouse T cell surface marker CD3 epsilon chain (CD3e) and CD8 alpha chain (CD8a) were chosen as test criteria for tumor-infiltrating lymphocytes, while IFNγRβ, CCR2, IL-2Rα and CCR5 were chosen as Th1-associated markers." (PMID 26417929, 2015). "Immunohistochemically, the tumor cells tend to express CD56, cytoplasmic CD3ε, CD2, cytotoxic granule proteins, granzyme B, and TIA-1 but not surface CD3." (PMID 23958352, 2013). "We found that lower levels of CD3ε, CD25, CD68, and ICAM-1 mRNA in BCC tumor biopsies at baseline predicted subsequent BCCs." (PMID 21980389, 2011). "The CD3-targeting property of CD3ε-Nb EVs combined with the characteristics of Nb-CAR.TCE construct may enhance memory CAR-T proportion, prolong anti-tumor immunity, and strengthen resilience against tumor antigen rechallenge." (PMID 41632088, 2026). "Incorporating the cytoplasmic tails of CD3ε, CD3γ, and CD3δ into CAR constructs has been shown to improve anti-tumor responses, while lowering cytokine secretion and early exhaustion compared to second-generation ζCARs, challenging the current gold-standard of ζ-based CAR T-cell therapy." (PMID 41601693, 2026). "On one hand, this may result from NFE2L1 deficiency leading to ROS accumulation, which could activate dendritic cells (DCs) or enhance tumor antigen release, thereby promoting the recruitment and activation of CD4+ T cells and CD8+ T cells (marked by CD3e)." (PMID 40677211, 2025).
tumor (continued). "Blinatumomab functions as a bispecific T-cell engager (BiTE), targeting tumor cells for destruction by simultaneously blinding to tumor-specific antigens (CD19 antigen on malignant B cells) and patients’ own T-cell receptors (typically CD3ε)." (PMID 40771820, 2025). "Tumor cell infiltration was also identified in 12 of 16 PB samples (0.24–74.0% in PB MNCs), five of which showed expansion of single-chain TCR tumor cells with CD3ε- CD4+ PD1high T-cell populations by FCM, consistent with the LN data." (PMID 38012392, 2024). "However, tracking tumor-recruited GFP-positive cells showed that Lyve-1+, Ter-119+ and CD3e+ subsets were segregated and localized to distinct intratumoral sites." (PMID 38640116, 2024). "TAG‐72/CD3ε FP T cells were also comprised of a higher CD8+ cytotoxic population, which may contribute to their faster in vitro tumor cell killing." (PMID 38023726, 2023). "In eMSC-treated mice, primary tumor CD8α+ T-cell percentages significantly increased, but, similarly to total CD3ε+ T-cell percentages, CD4+ T-cell depletion did not affect this increase." (PMID 37928528, 2023). "CD3E and CD3D play important roles in the positive regulation of T-cell activation and leukocyte cell–cell adhesion and are considered to be the main determinants of tumor immunotherapy efficacy." (PMID 37509334, 2023). "We previously reported that combining CD3ε and ζ ICD into a BB-based CAR improved tumor therapy." (PMID 37932456, 2023). "Interestingly, all tumor types showed strong correlation between IDO1 expression and CD3E and CD8A expressions." (PMID 35780226, 2022). "The residual tumor contains 94.7% (430 cells) of C1 TAMs, which express CD7, CD3D and CD3E." (PMID 35784460, 2022). "Using scRNAseq data from patient samples of primary and recurrent GBM (GSE154975), we identified multiple cell types based on markers from the original study: macrophages (ITGAM), T cells (CD3E), Tregs (CD4, CD3E, FOXP3), low-reads/dying cells (MALAT1), and tumor/normal brain cells (GFAP, SOX2)." (PMID 36591276, 2022). "The six critical genes, including CCR7, FCGR2B, BTLA, CD6, CD3D and CD3E, play important roles in favoring tumor progression and promoting negative immune-regulatory effects." (PMID 36291815, 2022). "Then, the qRT-PCR and western blotting were applied to detect the expression differences of CD2, CD3D, and CD3E in tumor tissues from recurrence and no recurrence patients." (PMID 36146529, 2022). "In the present study, the expression levels of CCL5, CXCR6 and CD3E exhibited a high correlation with the infiltration levels of CD8+ T cells, and the expression levels in HCC samples were lower than those that in adjacent non-tumor samples." (PMID 34218795, 2021). "Treatment with MFN, with or without IR, increased the percentage of total CD3e+ T cells infiltrating the tumor tissues, compared to the control." (PMID 33807943, 2021). "This tumor usually expresses CD2 and CD56 and lacks CD3 (but expresses cytoplasmic CD3ε)." (PMID 34350041, 2021). "TIGIT expression is greater in tumor regions than adjacent normal tissue, with levels higher than those quantified for PD-1, and its expression correlated with that of CD3ε but not with tumor grade or stage." (PMID 34831452, 2021). "In addition, we found a positive association between the gene expression level of CD2, CD3D, CD3E, and CXRC6 and the activated fraction of NK cells present in the tumor (CD2: Rho=0.442, CD3D: Rho=0.460, CD3E: Rho=0.423, and CXCR6: Rho=0.401)." (PMID 34692491, 2021). "We found that CD3E may be an indicator gene of the TME status of LGG patients and, by affecting the TME of LGG, can thereby change the tumor purity and affect the prognosis of patients." (PMID 34557404, 2021). "This may explain the previously noted positive correlation between IL-32 expression and individual genes indicative of lymphocyte infiltration, such as CD3E, CD8A, and IFNG, in bulk tumor samples." (PMID 32841222, 2020).
tumor (continued). "CD8+ T cell abundance was quantified from tumor RNAseq profiles using a four-gene expression signature score (referred to as TSIG) derived from the geometric mean of the normalized log2 read counts for the genes CD8A, CD8B, CD3D, and CD3E." (PMID 32117236, 2020). "We analyzed the immunological components in the tumor microenvironment of STS and found that the components of the antitumor immune response in STS were mainly CD3E/CD4/CD8A-labeled T cells, CD57-labeled NK cells, and CD45RO-labeled memory T cells that can secrete IFN-γ." (PMID 29896199, 2018). "For diagnosis, large neoplastic lymphoid cells of IVNKL are restricted to the lumen of small vessels and exhibit the phenotype of a true NK cell, characterized by tumor cells with a CD2+, cytoplasmic CD3ε + and CD56+ immunophenotype and germline configuration of the TCR gene." (PMID 26126576, 2015). "Therefore, we compared surface expression of CD3ε on T cells found in the tumor, the draining lymph node and the spleen of MCA-205-OVA tumor bearing mice." (PMID 24614600, 2014). "CD4 T cells exhibited no change in the surface expression of CD3ε between the tumor, draining lymph node and spleen." (PMID 24614600, 2014). "CD3ε, CD25, and ICAM-1 mRNA levels in tumor biopsies showed a significant correlation with histological tumor type (p = 0.003, p = 0.004, p = 0.03, respectively), with nodular tumor type having lower levels of gene expression than the superficial tumors or mixed tumors." (PMID 21980389, 2011). "Further analysis of the tumor cells revealed that after 2 days of culture, CD45+eGFPlow or + (p1, 2 & 3) and CD45−eGFPlow populations (p4) abnormally expressed all the lineage markers (CD3ε, CD11b, B220, Ter-119 and Gr-1) with variable levels." (PMID 17356702, 2007). "CD3-engaging BsAbs physically bridge cytotoxic T cells and tumor cells by binding CD3ε and a TAA, forming a functional immune synapse characterized by TCR microcluster assembly, LFA-1-ICAM-1 adhesion, and directed release of perforin and granzymes that induce tumor cell apoptosis." (PMID 41476945, 2025). "Thus, CD3ε-based CAR displayed a restrained surface expression on transduced T cells without significantly improving the threshold of tumor antigen density required for efficient killing." (PMID 39809749, 2025). "Modules 1–5 were rich in cytokines (e.g., IL6, IL10), cytokine receptors (e.g., CCR2, CCR4), and immune cell markers (e.g., CD3D, CD3E), indicating that the DEGs primarily regulate the immune microenvironment rather than tumor malignancy traits like proliferation and invasion." (PMID 38594692, 2024). "Analysis of GFP+ BM cells prior to injection determined that myeloid, erythroid, T-cell, and lymphatic markers were highly expressed (up to 90%) in vitro suggesting that low or absent expression of CD3e and Ter-119 in tumor-residing M-LECP was due to in vivo induced suppression." (PMID 38640116, 2024). "In total, five populations were designated tumour clusters, which had various features: (TumourC0) CD74 and APOD; (TumourC1) IF16, JUN and HSPA1A; (TumourC2) S100B and SCRG1; (TumourC3) NEAT1 and MALAT1; and (TumourC4) WFDC2 and RNASE1 (HLA‐DRA, CD68, CD3D, CD3E)." (PMID 37784253, 2023). "We could only detect the RNA and protein expression changes of CD3G, but not CD3D, CD3E or CD247 between tumor and normal tissues." (PMID 36176400, 2022). "Interestingly, it has been shown that cytotoxic human Tγδ cells did not require Nck recruitment to CD3ε to exert their tumor killing activity." (PMID 35432331, 2022). "In tumor tissues with a high SIGLEC1/CD68 ratio, there was an increase in the infiltration and function of cytotoxic lymphocytes, based on the expression of the T cell receptor CD3 complex subunit (CD3E), natural cytotoxicity receptor (NCR1), and interferon gamma (IFNG)." (PMID 36266311, 2022).
tumor (continued). "Additionally, functional annotation further suggested that CD3E, CD3D, and LCK were involved in positive regulation of T cell activation and leukocyte cell-cell adhesion that were known as the chief determinant for the efficacy of tumor immunotherapy." (PMID 33748188, 2021). "Although bsTCE with high affinity (KD < 1 nM) to CD3ε exhibited outstanding in vitro efficacy, those with a lower affinity (KD of 50–200 nM) minimized CD3-mediated plasma clearance or trapping of spleen and lymph nodes, showed efficient tumor distribution in vivo." (PMID 33808165, 2021). "The expression of T cell cytotoxicity (CD3G, CD3E, CD4, GZMA, PRF1 and TBX21), B cell MHC II and immune exhausted-related genes were abundant in metastatic sites; while MHC I inflammation related genes (HLA-B, HLA-C and IL-1A) were mostly higher in primary than recurrent tumor sites." (PMID 33476333, 2021). "Therefore, we made an audacious hypothesis that the reason why CD3E can be used as an independent molecular marker to test the prognosis of LGG patients is because it affects both immune cells and tumor cells." (PMID 34557404, 2021). "Flow-cytometric analysis suggested that tumor progression (from days 11 to 25) results in increased frequencies of CD45+CD11chighCD11b−MHCIIhigh lymphoid-DC, with the majority of DCs exhibiting a CD8α+ phenotype and expressed a significant amount of cd3ε (C1, C2)." (PMID 32582141, 2020). "However, blocking the Nck-CD3ε interaction in γδ T cells using the small molecule inhibitor AX-024 neither reduced the γδ T cells’ natural nor the Fab-enhanced tumor killing activity." (PMID 30038626, 2018). "Moreover, the percentage of CD3ε+ T cells that expressed cell surface CD25 was ∼40% of the total number of tumor infiltrating T cells and was greatly elevated in the draining (cervical) lymph node (dLN) (p<0.05) and tumor (p<0.01) when compared with the spleen of tumor bearing mice." (PMID 18431473, 2008). "These non-neoplastic cell populations that comprise the tumor microenvironment (TME) are identified by the expression of specific marker genes, such as PTPRC for myeloid cells and CD3E for T-cells, and contain cells captured across both datasets." (PMID 41501023, 2026). "TAG‐72/CD3ε FP T cells killed TAG‐72hi tumor cells as efficiently as TAG‐72 CAR‐T cells, whereas no lysis of TAG‐72lo tumor cells was observed." (PMID 38023726, 2023). "The bsAb in this approach contains both a T-cell binding domain and a tumor-binding domain, which can bind to CD3ε in the CD3ε-TCR complex and activate T cells without antigen presentation to kill tumor cells." (PMID 36341333, 2022). "The assessment of the new immune gene signature (CD2, CD3D, CD3E, and CXCRC6) in the CSCC cohort per tumor stage was not possible because sample size was too low for a meaningful analysis when we filtered data by stage." (PMID 34692491, 2021). "We found that sorted tumor-infiltrating CD33high cells expressed high levels of CD33 gene, while lacked gene expression of CD3E, CD8A and NCAM1 (gene for CD56), compared to CD8+ T cells." (PMID 33000418, 2021). "Global transcriptome studies on the spleen with and without the impact of the tumor surprisingly revealed up-regulated immune related functions in old hosts with CD2, CD3ε, CCL5, and CCL19 being key T-cell related factors." (PMID 26497558, 2015). "Immunohistochemically, the tumor cells were strong positive for CD56, CD3ε, TIA1, and weak positive for LMP1, and negative for CD5, CD8, CD20, CD79a, CgA, Syn, SCLC, CK, EMA, CD99, CD10, TdT, PAX-5, and BCL-6." (PMID 23958352, 2013). "As CD38 has broad expression in peripheral blood, we hypothesized that the proximity between the anti-CD3ε and anti-CD38 domains may trigger CD38+-cell depletion and higher T cell activation in the absence of tumor cells." (PMID 39261676, 2024).
tumor (continued). "Notably, the expression levels of CD3E, CCL5, CXCR6 and LCK in tumor samples and adjacent non-tumor samples were markedly different, and the results were consistent with the results of the analysis using TCGA." (PMID 34218795, 2021). "Too high of an affinity on the CD3ε arm of a TRBA can potentially lead to distribution into T-cell rich tissues such as lymph node and spleen rather than into tumor tissues and may potentially lead to toxicity." (PMID 31544847, 2019). "Furthermore, preliminary analysis of pre-treatment tumor samples with RNASeq has also revealed that responding patients had a higher number of tumor infiltrating lymphocytes (TIL) compared to non-responders, and CD3E expression." (PMID 34926242, 2021).